ENSG00000272237
Gene: Small nucleolar RNA gene on chromosome 2 (227,887,631 to 227,887,744, forward strand). Ensembl gene ENSG00000272237.
Homologues: Paralogues in human: SNORA25 (75% identical), SNORA25B (72% identical).